PLCE1 (phospholipase C epsilon 1)
Diseases named in the same sentence as PLCE1 in open-access papers (continued):
Sharing a sentence is not in itself a finding about the gene and the disease.
dengue (continued). "A previous genome-wide association study identified 2 susceptibility loci for severe dengue at MICB rs3132468 and PLCE1 rs3740360 and further work showed these mutations to be also associated with less severe clinical presentations." (PMID 28599625, 2017). "A recent study has shown that MICB and PLCE1 genes’ 3′- and 5′-UTR SNPs, which are associated with DSS, are implicated in the worsening of symptoms, from less severe symptoms of dengue to DSS, in children with dengue." (PMID 27038471, 2016). "The importance of MICB in dengue susceptibility was also indicated by GWAS with a large number of pediatric cases in Vietnam, where certain MICB and PLCE1 alleles showed a significant association with DSS." (PMID 24829565, 2014). "The present study in Thai patients with dengue successfully replicated the associations of MICB and PLCE1 SNPs with DSS that were reported by GWAS in Vietnamese patients." (PMID 24884822, 2014). "Consistent with the findings in older children, this pooled analysis revealed a significant association between dengue in infants and MICB rs3132468 (OR = 1.48; P = 0.0075), as well as PLCE1 rs3740360." (PMID 23536857, 2013). "We also note significant association between both SNPs (OR = 1.48; P = 0.0075 for MICB rs3132468 and OR = 0.75, P = 0.041 for PLCE1 rs3740360) and dengue in infants." (PMID 23536857, 2013). "This study confirms that the MICB rs3132468 and PLCE1 rs3740360 risk genotypes are not only associated with DSS, but are also associated with less severe clinical phenotypes of dengue, as well as with dengue in infants." (PMID 23536857, 2013). "In addition, an association was identified between PLCE1 rs3740360 and DHF in secondary dengue in Indonesian patients." (PMID 37958261, 2023). "There is no previous study that analyzed the association between PLCE1 and dengue severity stratified by primary or secondary dengue infections." (PMID 37958261, 2023). "PLCE1 rs3740360 was found to correlate with DHF in secondary dengue patients." (PMID 37958261, 2023). "A genome-wide association study has identified SNP rs3132468 in the MHC class I polypeptide-related sequence B (MICB) and SNP rs3765524 in the phospholipase C epsilon 1 gene (PLCE1) to be associated with DENV infection and severe dengue in a Vietnamese population." (PMID 32913345, 2020). "While previous work has demonstrated an association between genetic variants of MICB and PLCE1 and both severe and non-severe dengue, the functional basis of these associations is not clear." (PMID 28599625, 2017). "The role of PLCE1 in control of blood pressure warrants further exploration as it raises the possibility of some overlap in function in dengue given hypotension is seen in severe dengue." (PMID 28599625, 2017). "In the first genome-wide case–control genetic association study performed in dengue, several SNPs associated with DSS that are significant at the genome-wide level were identified, the most striking associations being SNPs in the MICB and PLCE1 genes." (PMID 26968374, 2016). "Although profound knowledge concerning the underlying molecular mechanisms for both dengue fever and DSS is still missing, functional polymorphism in MICB and PLCE1 genes alter the binding affinity of transcription factors in an allele-specific manner and shape susceptibility to DSS." (PMID 27038471, 2016). "Similarly, pooled analysis of pediatric and adult cohorts indicated a significant association between dengue cases without shock and PLCE1 rs3740360 (OR = 0.92; 95%CI: 0.85 – 0.99; P = 0.018)." (PMID 23536857, 2013). "The SNP associations identified at MICB (rs3132468) and PLCE1 (rs3740360) by the GWAS study were in the context of pediatric patients with DSS, leaving unanswered the question whether they are also associated with less severe clinical phenotypes of dengue." (PMID 23536857, 2013). "In total, 160 dengue patients from the Indonesian population were recruited and genotyped for MICB rs3132468 and PLCE1 rs3740360, rs3765524." (PMID 37958261, 2023).
dengue (continued). "Two thousand seven hundred forty two dengue cases were successfully genotyped at MICB rs3132468 and PLCE1 rs3740360." (PMID 28599625, 2017). "This study identified association of major histocompatibility complex (MHC) class I polypeptide-related sequence B (MICB), and phospholipase C, epsilon 1 (PLCE1) with DSS, and a subsequent study extended the findings to less severe pediatric dengue fever." (PMID 24517970, 2014). "Since the majority of Indonesian patients in this study had a prior infection with another serotype of dengue virus, i.e., secondary dengue (62.5%), we investigated correlations of the MICB or PLCE1 genotypes with the severity of dengue, stratified for primary and secondary infections." (PMID 37958261, 2023). "Across the 7 cohorts (4 pediatric and 3 adult) there were 297 DSS cases (161 pediatric and 136 adult), 3500 non-DSS dengue cases (2759 pediatric and 741 adult cases), and 164 cases of infants with dengue that were successfully genotyped at MICB rs3132468 and PLCE1 rs3740360." (PMID 23536857, 2013).
nephrotic syndrome (17 papers, 2009 to 2025). A collection of symptoms that include severe edema, proteinuria, and hypoalbuminemia; it is indicative of renal dysfunction. "Sanger sequencing and NGS panels have been used to identify PLCE1 mutations in nephrotic syndrome patients, while RT-qPCR has also been used for measuring PLCE1 mRNA expression in renal tissues." (PMID 41368354, 2025). "Four patients (LAMB2, LAMA5 and PLCE1 variants) presented with nephrotic syndrome or nephrotic range proteinuria." (PMID 40003707, 2025). "This explains why most patients with the extremely rare PLCE1-associated nephrotic syndrome are homozygous for the causal variant." (PMID 38051388, 2024). "Accordingly, incomplete penetrance with biallelic loss-of-function variants is exceptional: the early-onset PLCE1-associated nephrotic syndrome was only accepted after the identification of several families with non-penetrant phenotypes." (PMID 38051388, 2024). "Mutations in the PLCE1 gene disrupt this filter, leading to a disorder called nephrotic syndrome Researchers led by Heon Yung Gee at Yonsei University College of Medicine, Seoul, South Korea, have uncovered mechanisms underlying this malfunction." (PMID 32238860, 2020). "The role of PLCE1 in podocytes and the pathogenesis of nephrotic syndrome due to the loss of PLCE1 are not well understood." (PMID 32238860, 2020). "Mutations in PLCE1 are associated with nephrotic syndrome, a condition characterised by proteinuria, reduced vascular oncotic pressure and subsequent oedema." (PMID 28599625, 2017). "PLCε1 is implicated in CKD as PLCε1 gene mutations have been associated with early onset nephrotic syndrome, proteinuria, mesangial sclerosis, and glomerulosclerosis." (PMID 25861414, 2015). "Identification of additional proteins that are expressed in the podocyte and interact directly or indirectly with PLCε1 will be needed to help in the understanding of how mutations in PLCE1 cause nephrotic syndrome." (PMID 22693670, 2012). "Some heterozygous PLCE1 variants have been associated with an increased risk of nephrotic syndrome, indicating that gene-environment interactions may play a role in disease onset." (PMID 41368354, 2025). "Similarly, NPHS2 and PLCE1 mutations are linked to steroid-resistant nephrotic syndrome, with clear genotype-phenotype correlations." (PMID 41368354, 2025). "Loss-of-function mutations in PLCE1 have been detected in patients with nephrotic syndrome." (PMID 38390575, 2024). "Accordingly, whenever the transmission rate of a human disorder is not Mendelian, i.e., siblings with the same genotype at the primary locus present with discordant phenotypes, such as in PLCE1-associated nephrotic syndrome, an oligogenic inheritance can be assumed." (PMID 38051388, 2024). "PLCE1 encodes phospholipase C epsilon, and its mutations cause recessive nephrotic syndrome." (PMID 32238860, 2020). "As Rac1, Cdc42, and RhoA are implicated in the pathogenesis of nephrotic syndrome in mice and humans, we examined whether these Rho GTPases interact with PLCE1 in cultured podocytes." (PMID 32238860, 2020). "There is evidence that PLCE1 may be associated with pathogenesis; for example, positional cloning revealed that mutations in PLCE1 were responsible for the early-onset nephrotic syndrome and that the relatively frequent mutations in PLCE1 might cause isolated diffuse mesangial sclerosis (IDMS)." (PMID 22412849, 2012). "For example, steroids and immunosuppressants were discontinued in patient Pat-1117 with PLCE1-related nephrotic syndrome, and the patient was enlisted for renal transplant instead." (PMID 37344829, 2023). "Mutations in PLCE1 can induce isolated diffuse mesangial sclerosis and increase the incidence of steroid-resistant nephrotic syndrome, and PLCE1 genetic defects lead to congenital nephrotic syndrome." (PMID 35765945, 2022).
nephrotic syndrome (continued). "To address this, we investigated the function of PLCE1 in podocytes called glomerular epithelial cells, where the pathogenesis of nephrotic syndrome converges." (PMID 32238860, 2020). "The commonest genes associated with nephrotic syndrome differ at birth (NPHS1, NPHS2, WT1, LAMB2, PAX2, PLCE1), in childhood or adolescence (NPHS1, NPHS2, WT1, LAMB2, SMARCAL1, NUP107, TRPC6, PLCE1) and in adults (COL4A3-COL4A5, GLA, ACTN4, CD2AP, INF2, TRPC6)." (PMID 37578539, 2024). "Taken together, the loss of phospholipase activity is not sufficient to explain the pathogenesis of nephrotic syndrome resulting from PLCE1 mutations." (PMID 32238860, 2020).
colorectal cancer (16 papers, 2011 to 2025). A primary or metastatic malignant neoplasm that affects the colon or rectum. "Research indicates that lower expression of PLCE1 increases the risk of colorectal cancer, and overexpression of PLCE1 significantly reduces the proliferation of colorectal cancer cells and decreases their degree of malignancy." (PMID 40819340, 2025). "Liang's team found that circPLCE1 was also expressed at low levels in colorectal cancer cells and inhibited the proliferation and metastasis of colorectal cancer cells by encoding the PLCE1‐411aa protein." (PMID 37070530, 2023). "The PLCE1 rs2274223 is of particular interest and attention for its association with susceptibility of many types of cancer, like colorectal cancer 19, gastric cancer 18, 19, esophageal cancer, and several other digestive tract cancers 8, 20-24." (PMID 33162810, 2020). "For example, the PLCE1 rs2274223 A/G might reduce gene expression and the G allele might contribute to a higher risk of colorectal cancer." (PMID 33162810, 2020). "Here, we report a novel circular RNA circPLCE1 (hsa_circ_0019230) that facilitates the malignant progression of colorectal cancer (CRC) by repressing serine/arginine‐rich splicing factor 2 (SRSF2)‐dependent phospholipase C epsilon 1 (PLCE1) pre‐RNA splicing." (PMID 34173324, 2021). "In colorectal cancer, PLCE1 was slightly increased from 0.40 ± 0.03 in normal mucosa (n = 24) to 0.49 ± 0.04 in colorectal cancer (n = 45), and PRKCA was increased from 2.50 ± 0.51 in normal mucosa to 3.54 ± 1.34 in glioblastoma." (PMID 28402280, 2017). "Previous studies have shown that PLCE1 regulates inflammatory cytokine production, and thus, participates in skin and colorectal cancer formation." (PMID 28402280, 2017). "PLCE1 acts as a tumor suppressor in colorectal cancer but functions as an oncogene in ESCC and bladder cancers, indicating that the roles of PLCE1 in different tumors remain distinct." (PMID 29190930, 2017).
Diffuse mesangial sclerosis (9 papers, 2011 to 2025). Thickening and scarring (sclerosis) of the mesangium (a structure in the glomerulus). "PLCE1 (phospholipase C epsilon-1 gene): In phospholipase C epsilon-1 gene mutation, diffuse mesangial sclerosis histopathology is seen." (PMID 34925975, 2021). "We recommend PLCE1-related nephropathy to be included in the differential diagnosis in subjects with congenital/infantile nephrotic syndrome associated with diffuse mesangial sclerosis in particular." (PMID 32467597, 2020). "PLCE1 pathogenic variants are mostly associated with diffuse mesangial sclerosis histopathology." (PMID 32467597, 2020). "Recent evidence has demonstrated that PLCE1 mutations might cause the nephritic syndrome and diffuse mesangial sclerosis (DMS); however, few studies have investigated the association between genetic variants of PLCE1 and risk of human cancers." (PMID 21689432, 2011). "The severity spectrum of PLCE1-realted disease is broad, with some homozygous or compound heterozygous patients presenting with diffuse mesangial sclerosis, some with genetic FSGS and a minority of cases being asymptomatic." (PMID 40003707, 2025). "Diffuse mesangial sclerosis is associated with dominant pathogenic variants in WT1 (23.1%) and biallelic pathogenic variants in PLCE1 (17.8%), LAMB2 (13.6%), and NPHS1 (4.9%)." (PMID 32467597, 2020). "For instance, homozygous mutations in phospholipase C epsilon 1 (PLCE1, also known as NPHS3) were initially identified to cause a nonsyndromic, autosomal recessive form of diffuse mesangial sclerosis." (PMID 28752288, 2018). "Other important etiologies are phospholipase C epsilon-1 (PLCE1,) and Wilms tumor gene 1 (WT1,), mutations that typically cause diffuse mesangial sclerosis (DMS) and progressive impairment of renal function." (PMID 24682440, 2014).
gastric cardia adenocarcinoma (7 papers, 2011 to 2020). A carcinoma that arises from glandular epithelial cells of the cardia of stomach. "Upregulation of PLCE1 mRNA level is associated with longer survival in gastric cardia adenocarcinoma (GCA) and ESCC, while the transcript is downregulated in GCA and ESCC tumor tissue, which was confirmed by another study of ESCC patients." (PMID 28418898, 2017).
Hypertension (7 papers, 2017 to 2025). The presence of chronic increased pressure in the systemic arterial system. "Our analysis identified that the hypertension-susceptibility G allele of rs932764 located in an intron of PLCE1, which encodes for phospholipase C epsilon (PLCε), is associated with a significant reduction in risk of cardiotoxicity in our survivor population." (PMID 28851949, 2017). "In addition to PLCE1, carriers of the hypertension risk allele in ATP2B1 were at a reduced risk of cardiotoxicity." (PMID 28851949, 2017). "Hypertension-susceptibility alleles of PLCE1:rs9327264 and ATP2B1:rs17249754 were significantly associated with cardiotoxicity risk conferring a protective effect with a 64% (95% CI: 0.18–0.76, P = 0.0068) and 74% (95% CI: 0.07–0.96, P = 0.040) reduction in risk, respectively." (PMID 28851949, 2017). "In this study, two established hypertension-susceptibility alleles identified in the general population (PLCE1:rs932764 and ATP2B1:rs17249754) were also identified as predictors of cardiotoxicity risk in long-term childhood cancer survivors exposed to anthracyclines." (PMID 28851949, 2017). "Our findings demonstrate that the hypertension-susceptibility variants in PLCE1 and ATP2B1 confer a protective effect on risk of developing anthracycline-related cardiotoxicity, and functional analyses suggest that these genes are influenced by exposure to anthracyclines." (PMID 28851949, 2017). "The PLCE1-rs932764-G and ATP2B1-rs17249754-G variants, known for their role in hypertension, were significantly associated with a decreasing risk of cardiomyopathy (p = 0.006 and 0.04, respectively)." (PMID 40413218, 2025). "Variants at PLCE1 and HMGA2 were significantly associated with hypertension, diabetes, and anthropometric traits, such as body fat mass and waist circumference." (PMID 34127677, 2021). "In conclusion, two genetic variants in PLCE1 and ATP2B1 are inversely associated with hypertension and cardiotoxicity susceptibility." (PMID 28851949, 2017). "The gene‐wide result for PLCE1 is an example of such an observation, since it was previously reported for 38 other phenotypes, covering brain (e.g., migraine), cardiovascular (e.g., hypertension, blood pressure), and more general metabolic traits (e.g., BMI)." (PMID 35076988, 2022). "This inverse relationship between PLCE1:rs932764 and ATP2B1:rs17249754 associations with hypertension and cardiotoxicity suggests that the biological function of these two genes are different in the setting of hypertension verses response to anthracyclines resulting in cardiotoxicity." (PMID 28851949, 2017).
bladder cancer (6 papers, 2012 to 2020). "PLCε1 expression has been found to correlate with human bladder cancer, and the knockdown of PLCε1 in vitro and in vivo inhibited bladder tumor growth." (PMID 23077637, 2012). "However, PLCE1 is thought to act as an oncogene in bladder cancer, non-small cell lung cancer, skin cancer, and head and neck cancer." (PMID 28418898, 2017). "However, PLCE1 has also been identified as a novel candidate oncogene and a potential therapeutic target for several types of human cancers, such as bladder cancer and head and neck cancer." (PMID 26657507, 2016). "Similarly, PLCE1 knockdown in bladder cancer reduces proliferating cell nuclear antigen and cyclin D1 in the bladder tumor xenograft, leading to significant inhibition of cell proliferation and cell cycle arrest." (PMID 26657507, 2016). "PLCE1 silencing may also downregulate MMP and BCL2 gene expression, thereby reducing the invasiveness of bladder cancer cells." (PMID 26657507, 2016).
head and neck cancer (6 papers, 2015 to 2020). A primary or metastatic malignant neoplasm affecting the head and neck. "With head and neck cancer, effects of risk alleles of PLCE-1 were associated with cancers of the oral cavity, hypopharynx, or larynx but not with cancers of the oropharynx." (PMID 33194702, 2020). "A single-nucleotide polymorphism in PLCE-1, for instance, has been consistently found to be associated with the risk of ESCC, GCA, and head and neck cancer in the Chinese population." (PMID 33194702, 2020). "However, some studies indicated that PLCE1 acts as an oncogene in numerous cancers, such as non-small cell lung cancer and head and neck cancer." (PMID 30619753, 2018). "However, PLCE1 overexpression is found in bladder, head and neck cancers as well as ESCC, thus indicating the role of PLCE1 in tumorigenesis." (PMID 29190930, 2017).
cardia cancer (5 papers, 2012 to 2022). A malignant neoplasm involving the cardia of stomach. "The latest large meta-analyses confirmed the G allele of PLCE1 rs2274223 to be associated with an increased risk of cardia cancer (CC) rather than noncardia cancer (NCC)." (PMID 30931333, 2019). "Similarly, PLCE1 rs2274223 and PTGER4 and PRKAA1 rs13361707 were used to predict the risk of cardia cancer in populations with a hereditary background, who faced a greater than 3-fold higher risk (P < 0.05*)." (PMID 27127881, 2016). "Likewise, the significant association with PLCE1 rs2274223 G>A was noteworthy for all subjects, as well as for younger subjects, never smokers, never drinkers, those with BMI >24.0, cardia cancer or TNM stage III+IV diseases." (PMID 25658482, 2015). "Because the risk associated with the combined rs2274223 variant AG/GG genotypes and rs11187870 variant CG/CC genotypes was more evident in subjects with cardia cancer, we also compared the PLCE1 expression in subtypes of cardia gastric cancer and non-cardia gastric cancer." (PMID 22412849, 2012). "Also those with a hereditary background including the risk alleles PLCE1 rs2274223 and PTGER4/PRKAA1 rs13361707 were 3 times more susceptible to cardia cancer than those without." (PMID 27127881, 2016).